HOXC-AS3 (HOXC cluster antisense RNA 3)
Gene: Long non-coding RNA gene on chromosome 12 (53,981,509 to 53,986,339, reverse strand). Ensembl gene ENSG00000251151.
Diseases named in the same sentence as HOXC-AS3 in open-access papers:
HOXC-AS3 is named in the same sentence as 9 diseases in open-access papers, as found by Europe PMC text mining. Sharing a sentence is not in itself a finding about the gene and the disease. The quoted sentences say what the papers report.
breast carcinoma (4 papers, 2022 to 2023). "The significantly upregulated expression level of HOXC-AS3 is found in tissues of breast cancer, and the expression of HOXC-AS3 is well associated with the prognosis of breast cancer." (PMID 35692369, 2022). "HOXC-AS3 has been shown to promote the progression of breast cancer, gastric cancer and invasive mucinous adenocarcinoma of the lung." (PMID 35387975, 2022). "In addition, HOXC-AS3 was also highly expressed in breast cancer tissues, and further researches point out that HOXC-AS3 affected the proliferation of breast cancer cells by targeting thymidine kinase 1 (TK1)." (PMID 36613528, 2022). "This suggested that HOXC10, FXYD1, MT1X, and IGF2 may play an important role in the development of luminal A breast cancer under the regulation of HOXC-AS3, AC020907.2, AC026461.1, and AC132217.1." (PMID 35692369, 2022). "Moreover, the inhibition of HOXC-AS3 in breast cancer cells was observed to induce cell apoptosis via the Y-box binding protein 1 (YBX1)/TK1 axis." (PMID 36613528, 2022). "In breast cancer, a high level of HOXC-AS3 is highly correlated with a poor prognosis." (PMID 35387975, 2022). "Furthermore, they indicated that HOXC-AS3 could significantly suppress breast cancer progression, which suggests the potential of anti-HOXC-AS3 for breast cancer treatment." (PMID 37161350, 2023).
gastric cancer (4 papers, 2018 to 2025). A primary or metastatic malignant neoplasm involving the stomach. "HOXC-AS3 is significantly increased in gastric cancer tissues and is correlated with clinical outcomes of gastric cancer." (PMID 30286788, 2018). "Gastric cancer cell lines expressed significantly higher levels of HOXC-AS3 than a normal gastric epithelium cell line (GES-1)." (PMID 30286788, 2018). "Specifically, HOXC-AS3 binds to YBX1, leading to transcriptional regulation of multiple genes associated with cell proliferation and migration—such as MMP7, WNT10B, and HDAC5—in gastric cancer cells, thereby promoting malignant behaviors." (PMID 41312360, 2025). "HOXC-AS3 is upregulated in gastric cancer cells and promotes tumorigenesis." (PMID 35387975, 2022). "HOXC-AS3 was elevated in GC (gastric cancer) in a prior study by Erbao Zhang, and when combined with YBX1 could facilitate GC cell proliferation and migration." (PMID 36031658, 2022). "Together, our data demonstrate that abnormal histone modification-activated HOXC-AS3 may play important roles in gastric cancer oncogenesis and may serve as a target for gastric cancer diagnosis and therapy." (PMID 30286788, 2018). "To explore the role of HOXC-AS3 in GC, we examined the HOXC-AS3 expression levels in gastric cancer cell lines." (PMID 30286788, 2018). "HOXC-AS3 has been shown to interact with Y-box binding protein-1 (YBX1), a transcription factor, in gastric cancer cells, and our bioinformatic analysis (RNAInter) identified this interaction in NSCLC cells as well." (PMID 35387975, 2022).
glioma (1 paper, 2022). A benign or malignant brain and spinal cord tumor that arises from glial cells (astrocytes, oligodendrocytes, ependymal cells). "In this research, we discovered that HOXC-AS3 was over-expression in glioma cells and tissues and was associated with prognosis." (PMID 35402226, 2022). "The results demonstrated that the expression level of HOXC-AS3 in the glioma cell lines was elevated than that in the NHAs." (PMID 35402226, 2022). "The function of HOXC-AS3 on glioma cell proliferation, migration, invasion, and tumor growth in vivo was also examined." (PMID 35402226, 2022). "We also collected clinical samples during surgery, tested the expression of HOXC-AS3 in glioma and normal brain tissues by qRT–PCR and found that the expression level of HOXC-AS3 was similar to that predicted by online databases." (PMID 35402226, 2022). "Current research suggests that HOXC-AS3 targets miR-216 as a sponge and that miR-216 regulates glioma progression by acting on F11R." (PMID 35402226, 2022). "At present, our research demonstrates that the expression level of HOXC-AS3 in glioma tissues and cell lines is elevated than that in normal tissues and cells." (PMID 35402226, 2022). "Then, we examined the expression of HOXC-AS3 in normal human astrocytes (NHAs) and glioma cell lines (LN229, T98G, A172, U87, and U251)." (PMID 35402226, 2022). "Our FISH assay identified that HOXC-AS3 is principally expressed in the cytoplasm of glioma cells." (PMID 35402226, 2022). "In this research, we demonstrate that miR-216 could interact with HOXC-AS3 and that the expression of miR-216 was negatively correlated with HOXC-AS3 expression in glioma cells and clinical samples." (PMID 35402226, 2022). "Furthermore, we disclosed that HOXC-AS3 modulates F11 receptor (F11R) expression by sponging miR-216 and facilitating glioma cell proliferation, migration, invasion, and tumor growth in vivo." (PMID 35402226, 2022). "Accordingly, it is significant to probe the potential mechanism of HOXC-AS3 in glioma." (PMID 35402226, 2022). "Based on these studies, HOXC-AS3 may function via a ceRNA mechanism in glioma." (PMID 35402226, 2022). "An shRNA against HOXC-AS3 (sh-HOXC-AS3), and sh-HOXC-AS3 along with miR-216 inhibitors were transfected into glioma cells." (PMID 35402226, 2022). "HOXC cluster antisense RNA 3 (HOXC-AS3) is a long noncoding RNA (lncRNA) that plays a crucial role in various tumors; nevertheless, its role in glioma and its mechanism have not been completely elucidated." (PMID 35402226, 2022).
lymph node metastasis (1 paper, 2022). "Moreover, the high expressions of HOXC cluster antisense RNA 3 (HOXC-AS3), LINC02273, and maternally expressed gene 3 (MEG3) are strongly associated with TNM stage, lymph node metastasis, and metastasis." (PMID 36613528, 2022).
ovarian carcinoma (1 paper, 2024). A malignant neoplasm originating from the surface ovarian epithelium. "As an example of these lncRNAs, lncRNA HOXC cluster antisense RNA 3 (HOXC-AS3) has been reported to facilitate progression of gastric and ovarian cancer types by modulating cell proliferation." (PMID 38842683, 2024).
tumor (4 papers, 2018 to 2024). "The results showed that the expression of HOXC-AS3 was related to tumor size and international federation of gynecology and obstetrics (FIGO) stage (p < 0.05)." (PMID 38842683, 2024). "By analyzing the differentially expressed lncRNA data in the TCGA database, we discovered that the expression of HOXC-AS3 in tumor tissues was significantly higher than that in normal tissues." (PMID 35402226, 2022). "Our study, together with previous research, indicates that HOXC-AS3 functions as a tumour oncogene in many types of cancers." (PMID 35387975, 2022). "One tumor tissue showed an upregulation of HOXC-AS3 greater than 521-fold relative to normal tissue." (PMID 30286788, 2018). "Therefore, we conclude that HOXC-AS3 promotes NSCLC tumour growth and metastasis in vivo by increasing HOXC8 expression." (PMID 35387975, 2022). "Therefore, we concluded that knockdown of HOXC-AS3 inhibits NSCLC tumour growth and metastasis in vivo." (PMID 35387975, 2022). "Knockdown of HOXC-AS3 strongly suppressed NSCLC cell proliferation, migration and invasion, and it inhibited tumour growth and metastasis in vivo, while overexpression further facilitated NSCLC cell proliferation, migration and invasion." (PMID 35387975, 2022). "Knockdown of HOXC-AS3 suppressed NSCLC cell proliferation, migration and invasion, as well as tumour growth and metastasis in vivo." (PMID 35387975, 2022). "Elevated expression of HOXC-AS3/YBX1/HOXC8 occurs in NSCLC cells, and inhibition of their expression significantly suppresses cancer cell proliferation, migration and invasion, resulting in attenuated tumour growth and metastasis in vivo." (PMID 35387975, 2022).
cancer (3 papers, 2018 to 2022). A tumor composed of atypical neoplastic, often pleomorphic cells that invade other tissues. "In addition, HOXC-AS3 has been implicated in various types of cancers." (PMID 35387975, 2022). "RNA-seq found that knockdown of HOXC-AS3 affected key cancer-related genes, such as p21, FAS, and CCND1." (PMID 30286788, 2018).
HOXC-AS3 also shares sentences with these, for which no sentence is quoted: cervical squamous cell carcinoma (1 paper); gastric adenocarcinoma (1).